TRBJ2-5 (T cell receptor beta joining 2-5)
Description:
J region of the variable domain of T cell receptor (TR) beta chain that participates in the antigen recognition. Alpha-beta T cell receptors are antigen specific receptors which are essential to the immune response and are present on the cell surface of T lymphocytes. Recognize peptide-major histocompatibility (MH) (pMH) complexes that are displayed by antigen presenting cells (APC), a prerequisite for efficient T cell adaptive immunity against pathogens. Binding of alpha-beta TR to pMH complex initiates TR-CD3 clustering on the cell surface and intracellular activation of LCK that phosphorylates the ITAM motifs of CD3G, CD3D, CD3E and CD247 enabling the recruitment of ZAP70. In turn ZAP70 phosphorylates LAT, which recruits numerous signaling molecules to form the LAT signalosome. The LAT signalosome propagates signal branching to three major signaling pathways, the calcium, the mitogen-activated protein kinase (MAPK) kinase and the nuclear factor NF-kappa-B (NF-kB) pathways, leading to the mobilization of transcription factors that are critical for gene expression and essential for T cell growth and differentiation. The T cell repertoire is generated in the thymus, by V-(D)-J rearrangement. This repertoire is then shaped by intrathymic selection events to generate a peripheral T cell pool of self-MH restricted, non-autoaggressive T cells. Post-thymic interaction of alpha-beta TR with the pMH complexes shapes TR structural and functional avidity.
Synonyms: TRBJ25; TCRBJ2S5
Gene: T-cell receptor joining (J) gene on chromosome 7 (142,797,119 to 142,797,166, forward strand). Ensembl gene ENSG00000211769.
Subcellular location: Cell membrane